HNRNPA1L2 (heterogeneous nuclear ribonucleoprotein A1 like 2)
Description:
Involved in the packaging of pre-mRNA into hnRNP particles, transport of poly(A) mRNA from the nucleus to the cytoplasm and may modulate splice site selection.
Synonyms: LOC144983
Tractability: PROTAC: ubiquitination databases record sites on it.
Gene: Protein-coding gene on chromosome 13 (52,642,431 to 52,643,773, forward strand). Ensembl gene ENSG00000139675.
Subcellular location: Nucleus; Cytoplasm
Subcellular location (Human Protein Atlas): Nucleoplasm
Gene Ontology:
Molecular function: protein binding; mRNA 3'-UTR binding; nucleic acid binding; RNA binding
Biological process: mRNA splicing, via spliceosome
Cellular component: catalytic step 2 spliceosome; cytoplasm; nucleus
Genetic constraint (gnomAD): Loss-of-function variants: 10 observed, 16.48 expected, observed/expected ratio (o/e) 0.61, 90% interval 0.37 to 1.03. The upper end of that interval is the gene's LOEUF score, 1.03, which puts it in group 4 of 6, group 1 being the genes least tolerant of losing a copy. Missense variants: 301 observed, 358.32 expected, observed/expected ratio (o/e) 0.84, 90% interval 0.76 to 0.92. Synonymous variants: 122 observed, 127.6 expected, observed/expected ratio (o/e) 0.96, 90% interval 0.82 to 1.11.
Homologues: Orthologues: zebrafish hnrnpa1b (72% identical). Paralogues in human: HNRNPA1 (97% identical), HNRNPA1L3 (96% identical), HNRNPA3 (78% identical), HNRNPA2B1 (66% identical), HNRNPA0 (39% identical), HNRNPD (34% identical), MSI2 (33% identical), MSI1 (32% identical), HNRNPDL (31% identical), DAZAP1 (31% identical), HNRNPAB (30% identical), NUCLEOLIN (30% identical), and 24 more.
Diseases named in the same sentence as HNRNPA1L2 in open-access papers:
HNRNPA1L2 is named in the same sentence as 3 diseases in open-access papers, as found by Europe PMC text mining. Sharing a sentence is not in itself a finding about the gene and the disease. The quoted sentences say what the papers report.
COVID-19 (1 paper, 2023). A disease caused by infection with severe acute respiratory syndrome coronavirus 2. "Interestingly, miR-6741 was recently described as a potential biomarker for the severity of COVID-19, where a transient upregulation after dexamethasone treatment was associated with a poor prognosis; APOBEC3H and HNRNPA1L2, involved in antiviral defense, were identified as target genes." (PMID 38136163, 2023).
HNRNPA1L2 also shares sentences with these, for which no sentence is quoted: cancer (1 paper); giant cell tumor of bone (1).